LCT (lactase)
Description:
Broad specificity glycosidase of the intestinal brush border membrane that hydrolyzes lactose, the main sugar in mammalian milk, to produce D-glucose and D-galactose. The mature protein is composed of two domains that catalyze the hydrolysis of beta-glucopyranosides and beta-galactopyranosides, with a preference for hydrophilic aglycones (in lactose and cellobiose) for one domain and hydrophobic aglycones (in phlorizin and glycosylceramides) for the other.
Synonyms: LPH; LAC; LPH1
Tractability: Antibody: UniProt places it where antibodies can reach, with high confidence; its Gene Ontology location is reachable by antibodies, with high confidence; UniProt predicts a signal peptide or a membrane-spanning region. PROTAC: a small molecule that binds it is known.
Target class: Enzyme; Hydrolase
Gene: Protein-coding gene on chromosome 2 (135,787,850 to 135,837,184, reverse strand). Ensembl gene ENSG00000115850.
Subcellular location: Apical cell membrane
Pathways (Reactome):
Digestion and absorption: Digestion of dietary carbohydrate
Disease: Intestinal saccharidase deficiencies
Gene Ontology:
Molecular function: beta-glucosidase activity; cellobiose glucosidase activity; lactase activity; phlorizin hydrolase activity; protein homodimerization activity; galactosylceramidase activity; glucosylceramidase activity; hydrolase activity, hydrolyzing O-glycosyl compounds
Biological process: cellobiose catabolic process; lactose catabolic process; quercetin catabolic process; glycosylceramide catabolic process; carbohydrate metabolic process
Cellular component: apical plasma membrane; external side of apical plasma membrane; plasma membrane
Genetic constraint (gnomAD): Loss-of-function variants: 90 observed, 173 expected, observed/expected ratio (o/e) 0.52, 90% interval 0.44 to 0.62. The upper end of that interval is the gene's LOEUF score, 0.62, which puts it in group 2 of 6, group 1 being the genes least tolerant of losing a copy. Missense variants: 1,813 observed, 2,495.6 expected, observed/expected ratio (o/e) 0.73, 90% interval 0.7 to 0.75. Synonymous variants: 844 observed, 989.71 expected, observed/expected ratio (o/e) 0.85, 90% interval 0.81 to 0.9.
Homologues: Orthologues: chimpanzee LCT (99% identical), macaque LCT (96% identical), dog LCT (84% identical), rabbit LPH (83% identical), mouse Lct (80% identical), rat Lct (79% identical), tropical clawed frog lct (58% identical), tropical clawed frog lct.2 (55% identical), zebrafish lct (53% identical), zebrafish LCT (48% identical), Drosophila melanogaster CG9701 (12% identical), Caenorhabditis elegans klo-2 (9% identical), and 1 more. Paralogues in human: KL (20% identical), KLB (20% identical), LCTL (13% identical), GBA3 (11% identical).
Diseases named in the same sentence as LCT in open-access papers:
LCT is named in the same sentence as 104 diseases in open-access papers, as found by Europe PMC text mining. Sharing a sentence is not in itself a finding about the gene and the disease. The quoted sentences say what the papers report.
lactose intolerance (144 papers, 1997 to 2026). "For instance, mutations of the LCT gene that encodes an enzyme known as lactase, responsible for the breaking of the sugar called lactose, have been associated with lactose intolerance." (PMID 41567168, 2026). "Lactose intolerance (LI) is characterized by an inability to completely digest lactose, primarily owing to lactase deficiency, whereas lactose malabsorption occurs when lactose is not easily digested due to low lactase levels." (PMID 41351747, 2025). "Conversely, populations with low lactase persistence allele frequencies are more likely to experience an increase in lactose intolerance symptoms, such as bloating, diarrhea, and gas." (PMID 40896188, 2025). "Has one of the following disorders: lactose intolerance, the Lapp lactase deficiency or glucose-galactose malabsorption." (PMID 40010822, 2025). "Lactose intolerance is widely recognized as resulting from decreased production of lactase (encoded by a variant of the lactase LCT gene), which typically occurs after weaning during childhood." (PMID 39320101, 2024). "Several studies have reported that lactase supplementation can alleviate the symptoms associated with neonatal lactose intolerance, such as reducing the duration of diarrhea and relieving intestinal colic." (PMID 39201948, 2024). "Low levels of the enzyme lactase cause lactose intolerance, which makes it difficult to digest lactose contained in dairy products." (PMID 39796443, 2024). "Neonatal lactose intolerance refers to the deficiency or reduced activity of lactase in the neonatal digestive system, which results in impaired lactose digestion and absorption." (PMID 39201948, 2024). "Neonatal lactose intolerance is chiefly characterized by developmental and secondary lactase deficiency." (PMID 39201948, 2024). "Lactase (β-galactosidase) supplementation, a key component of digestive enzyme therapy, addresses lactose intolerance resulting from the genetic basis for lactase deficiency." (PMID 38406012, 2024). "This review focuses on primary lactose intolerance caused by the cessation of lactase production post-weaning, which is the principal cause of lactose malabsorption." (PMID 38613035, 2024). "Congenital lactose intolerance or congenital/permanent lactase deficiency is due to a defect or mutation in the gene responsible for lactase synthesis, i.e., the lactase phlorizin hydrolase (lph) gene located in the human chromosome 2q21.3." (PMID 38337698, 2024). "Our findings support that oral lactase treatment is effective in infants with lactose intolerance, a potential cause of infantile colic, particularly in those 0–6 months old and exclusively breastfed." (PMID 39201943, 2024). "Lactose intolerance (LI) is a prevalent condition characterized by gastrointestinal symptoms after lactose consumption due to a deficiency of lactase." (PMID 39320101, 2024). "The most reliable diagnostic technique for lactose intolerance is non-invasive hydrogen breath testing, and management of this condition requires a lactose-free diet or the administration of lactase enzyme supplements." (PMID 38257158, 2024). "Measuring lactase activity in endoscopic duodenal biopsies is another diagnostic tool for lactose intolerance (LI)." (PMID 38613035, 2024). "Lactose intolerance, or hypolactasia, is a common medical condition characterized by malabsorption of lactose in the small intestine caused by low levels of lactase, the enzyme that catalyzes the breakdown of lactose." (PMID 39605839, 2024). "Lactose intolerance, appearing in 70% of worldwide populations, is mainly a genetic deficiency of the lactose-degrading enzyme lactase." (PMID 37761406, 2023). "Lactase deficiency causes lactose intolerance which is an abnormal condition characterized by the deficiency of lactase in the small intestine leading to the failure in digesting dairy products by the human body." (PMID 37347747, 2023).
lactose intolerance (continued). "Alterations in gut microbiota cocktail and function have also been linked to changes in LCT gene expression and lactase activity, highlighting the multifactorial factors in lactose intolerance." (PMID 37447285, 2023). "Lactose intolerance is a disorder of intestinal digestion due to the decrease or complete loss of lactase phlorizin hydrolase (LPH) activity, leading to disability of lactose absorption and osmotic diarrhea." (PMID 37823142, 2023). "In this context, consumption of kefir has been shown to improve symptoms of lactose intolerance, a worldwide syndrome that affects about 70% of the adult population, which is caused by a decreased production of lactase in the small intestine." (PMID 35406987, 2022). "A variety of pathological conditions leading to small intestinal damage, including celiac disease, Crohn's disease, and small bowel bacterial overgrowth, can lead to decreased expression of lactase, from causing transient lactose intolerance to diarrhea." (PMID 36171559, 2022). "The resulting inability to digest lactose properly is referred to as lactose intolerance, due to lactase deficiency." (PMID 36149331, 2022). "It has been proven that primary lactose intolerance is related to a single-nucleotide polymorphism of the lactase (LCT) gene." (PMID 35565753, 2022). "The underlying cause of lactose intolerance, a condition in which clinical symptoms are causally related to lactose consumption, is a lack or deficiency of lactase, a brush border enzyme of the small intestine." (PMID 36296945, 2022). "The activity of lactase, a lactose-degrading enzyme at the brush border of the small intestinal mucosal epithelium, is deficient or reduced in people with hypolactasia or lactose intolerance." (PMID 36568903, 2022). "A lactase deficiency results in a lactose intolerance that has an autosomal recessive mode of inheritance and is associated with homozygosity of the gene." (PMID 33547344, 2021). "Lactase administration or pretreated food product with lactase enzyme is a practical therapeutic approach to control symptoms of lactase deficiency and lactose intolerance." (PMID 33490624, 2021). "LCT is an enzyme that converts lactose to glucose and galactose, and LCT deficiency induces lactose intolerance and is possibly involved in allergy by modulating immunity." (PMID 34445011, 2021). "If IBS was caused by lactase deficiency presenting as lactose malabsorption, lactase supplementation would be expected to lead to clinical improvement, as is the case of patients with lactose intolerance as an independent clinical entity." (PMID 32104635, 2020). "Genetic single nucleotide polymorphisms (SNPs) (C>T-13910 and G>A-22018), located upstream to the lactase gene, have been strongly associated with adult lactose intolerance / persistence in several populations." (PMID 32012749, 2020). "A study showed that the incidence of lactase deficiency was 38.5% and the proportion of lactose intolerance was 12.2% in Chinese 3–5-year-old children." (PMID 32854304, 2020). "In China, a study showed that the incidences of lactase deficiency and lactose intolerance were 38.5% and 12.2% in 3–5-year-old children, respectively." (PMID 32854304, 2020). "Lactose intolerance is characterized by a deficiency in the lactase enzyme, leaving undigested lactose in the GI tract resulting in distress." (PMID 30819184, 2019). "Lactose intolerance occurs as a result of decreased expression of intestinal lactase, and is often associated with lactose-induced abdominal pain, diarrhea, and intestinal distension." (PMID 30332787, 2018). "In contrast, using a candidate-gene approach, we found novel evidence that circulating C17:0 levels are associated with genetic variation in LCT, the gene responsible for adult-onset lactose intolerance." (PMID 29738550, 2018).
lactose intolerance (continued). "In China, for children aged 3–5, 7–8 and 11–13, the prevalence of lactase deficiency was 38.5%, 87.6%, and 87.8%; and the prevalence of lactose intolerance was 12.2%, 32.2%, and 29%, respectively." (PMID 28872591, 2017). "It is important to distinguish lactase deficiency from lactose malabsorption and lactose intolerance." (PMID 27207411, 2016). "Lactose intolerance related to primary or secondary lactase deficiency is characterized by abdominal pain and distension, borborygmi, flatus, and diarrhea induced by lactose in dairy products." (PMID 26393648, 2015). "Whatever the cause, lactase deficiency results in unabsorbed lactose being present in the intestinal tract, which has effects that can lead to symptoms of lactose intolerance in susceptible individuals." (PMID 26393648, 2015). "The most common cause of lactose intolerance is lactase deficiency, a decreased production of the enzyme lactase in the small intestinal villi." (PMID 24967391, 2014). "Adult-type hypolactasia or lactose intolerance (OMIM #223100) is a worldwide common phenotype determined by lactase deficiency, it is due to lactase activity decline after weaning." (PMID 23029545, 2012). "One of these enzymes is lactase, which breaks down the milk sugar lactose; lactase deficiency results in lactose intolerance." (PMID 15706765, 1997). "When lactase activity is insufficient, undigested lactose proceeds to the colon where it is fermented by the gut flora, generating gas that trigger the uncomfortable symptoms associated with lactose intolerance." (PMID 41843249, 2026). "We found that all individuals with sufficient genomic coverage carried ancestral alleles at SNPs associated with lactase persistence, suggesting that they might have suffered from lactose intolerance in adulthood." (PMID 41398308, 2025). "Furthermore, some of the symptoms observed in this study are attributable to or associated with lactose intolerance, the most common cause of which is lactase deficiency or insufficient lactase activity." (PMID 40647268, 2025). "Consequently, it is unsurprising that lactase persistence alleles are rare among Arctic people, and lactose intolerance is common in adulthood." (PMID 40896188, 2025). "Interestingly, genomic data reveal that several individuals carried ancestral alleles at SNPs associated with lactase persistence, indicating a likely susceptibility to lactose intolerance in adulthood." (PMID 41398308, 2025). "Treatment of the underlying disease in secondary lactose intolerance might restore the lactase level and improve clinical manifestations of LI." (PMID 38337698, 2024). "In addition to lactase deficiency, bacterial fermentation ability also contributes significantly to lactose intolerance." (PMID 39320101, 2024). "The most frequently met form of lactose intolerance is primary lactose intolerance (adult-type hypolactasia), which is inherited in an autosomal recessive manner and, in the Caucasian population, is associated with a C/T polymorphism of the lactase gene." (PMID 39796443, 2024). "Lactase gene polymorphisms have been widely used to predict lactose intolerance." (PMID 37444291, 2023). "Lactose intolerance (LI) is the symptomatic condition that characterizes those individuals who are unable to digest lactose into glucose and galactose, due to a partial or total deficiency of the enzyme lactase-phlorizin hydrolase (LPH)." (PMID 34574346, 2021). "Lactose intolerance (LI) is characterized by the presence of primarily gastrointestinal clinical signs resulting from colonic fermentation of lactose, the absorption of which is impaired due to a deficiency in the lactase enzyme." (PMID 32443748, 2020). "The restriction of milk exosomes to the postnatal period has been secured by physiological lactose intolerance that appears after weaning in all mammals except lactase (LCT)-mutated humans that could persistently abuse this postnatal epigenetic doping system." (PMID 30602375, 2019).
lactose intolerance (continued). "The extent to which undigested lactose causes the lactose intolerance symptoms depends on a number of factors, including amount of lactose ingested, small-intestinal lactase activity, gastric emptying rate, transit time, and gastrointestinal microflora composition." (PMID 27207411, 2016). "Certainly, it is not possible to make a definitive diagnosis on clinical presentation alone because double-blind trials have shown that the association of self-reported lactose intolerance and the occurrence of symptoms after lactose ingestion are very poor, even in patients with lactase deficiency." (PMID 26393648, 2015). "In CDpatients, lactose intolerance could be owing to secondary lactase deficiency and toprimary lactase deficiency but the hereditary lactase deficiency is frequent in CDchildren as in control population." (PMID 25120893, 2014). "Moreover, 96 (34.53%) respondents stated that prophylactic lactase supplementation can be given to newborns at high risk of lactose intolerance, and 67 (24.1%) respondents indicated that supplementation of lactase should only be administered to newborns diagnosed with lactose intolerance." (PMID 39201948, 2024). "Moreover, such a diet may consequently lead to the disappearance of the production of the enzyme lactase that causes lactose intolerance." (PMID 36670587, 2022). "In some participants, the association between symptoms and dairy products could possibly be attributable to lactose intolerance, a term used to describe the onset of GI symptoms in response to lactose consumption, usually due to lactase deficiency induced malabsorption." (PMID 33003341, 2020). "Four types of lactase deficiency may lead to lactose intolerance." (PMID 26404364, 2015). "We examined genetic polymorphisms that might influence calcium metabolism: lactase (LCT) gene 13910 C/T polymorphism causing lactose intolerance and calcium-sensing receptor (CaSR) gene A986S polymorphism as a responsible factor for the altered cellular calcium sensation." (PMID 18980667, 2008). "Lactase enzyme-based products experience challenges including residual lactose that result in lactose intolerance." (PMID 42042181, 2026). "Management of lactose intolerance often involves dietary restrictions and the prescription of formulations that contain lactase." (PMID 41843249, 2026). "The lactase enzyme is primarily used in the dairy industry to remove lactose from milk, producing lactose-free products for individuals with lactose intolerance." (PMID 41471052, 2025). "These diseases or conditions cause damage to the small intestinal mucosa or interfere with the synthesis of lactase, resulting in decreased lactase activity and thereby leading to secondary lactose intolerance." (PMID 40647268, 2025). "We have defined adult-onset lactose intolerance as lactose intolerance manifesting in adulthood and likely resulting from age-related decline in lactase production." (PMID 41502574, 2025). "A decrease in the lactase enzyme, which occurs after weaning, and damage to the lining of the digestive tract can be responsible for lactose intolerance." (PMID 41280398, 2025). "Congenital lactose intolerance is caused by LOF mutations within LCT, which encodes the lactase enzyme." (PMID 41502574, 2025). "Primary lactose intolerance results from decreased synthesis of lactase, either at the transcriptional or translational level." (PMID 41008568, 2025). "The primary approach to managing lactose intolerance in individuals is to substitute normal dairy products with low-lactose and lactose-free alternatives; dairy products supplemented with exogenous lactase or probiotics." (PMID 41280398, 2025). "Secondary lactose intolerance is attributable to a partial, rarely complete decrease in lactase activity in the course of diseases, leading to damage to the small intestinal mucosa or a reduction in its surface area." (PMID 39796443, 2024).